MAPK8IP1P1 (mitogen-activated protein kinase 8 interacting protein 1 pseudogene 1)
Synonyms: MAPK8IPP; PRKM8IPP
Gene: Processed pseudogene on chromosome 17 (46,243,606 to 46,245,044, forward strand). Ensembl gene ENSG00000262500.
Diseases named in the same sentence as MAPK8IP1P1 in open-access papers:
MAPK8IP1P1 is named in the same sentence as 2 diseases in open-access papers, as found by Europe PMC text mining. Sharing a sentence is not in itself a finding about the gene and the disease. The quoted sentences say what the papers report.
diabetes (1 paper, 2024). "Loci for the other genes—PTP4A1, APOBR, BMS1P4-AGAP5, MAPK8IP1P1, GYS2, FAM25C, and GK5–were formerly associated with traits involved with comorbidities of OSA, i.e., BMI, weight, triglycerides, blood pressure, stroke, brain volume, cortical thickness, mood, insulin, and diabetes." (PMID 39457448, 2024).
MAPK8IP1P1 also shares sentences with these, for which no sentence is quoted: Stroke (1 paper).